BCL2 (BCL2 apoptosis regulator)
Diseases named in the same sentence as BCL2 in open-access papers (continued):
Sharing a sentence is not in itself a finding about the gene and the disease.
tumor (continued). "The expression of BCL‐2 increased in tumour tissues stained by immunofluorescence." (PMID 38037859, 2024). "Erianin may exerted its anti-tumor effect in DDP-resistant LUAD cells by regulating the Wnt3/β-Catenin/Survivin/Bcl-2/Caspase-3/Cyclin D1 axis." (PMID 39605083, 2024). "CASP3 is activated, while BCL2 expression is attenuated in tumor cell death." (PMID 38361755, 2024). "Triptolide suppresses Bcl2 to assert its anti-tumor action, according to prior studies." (PMID 38293343, 2024). "Furthermore, some studies highlighted that SCFAs can induce apoptosis in tumor cells through the expression of p21 and Bcl-2, and the downregulation of cyclin B1, A, and D1." (PMID 38792153, 2024). "In MM, Notch signaling supports tumor cell survival by interacting with Bcl-2 to inhibit apoptosis." (PMID 39684550, 2024). "BCL2 is an apoptosis-inhibiting gene and is considered an influential factor in tumor cell production and proliferation, and it may play a role in the HF growth cycle and morphogenesis." (PMID 38674344, 2024). "In MDA-MB-231 cells, all the tested genes were significantly downregulated in si-Bcl-2 condition, except for TEAD4, while only for TEAD2 transcript a significant modulation was observed in Bcl-2 silenced H460 cells, suggesting that Bcl-2 can affect Hippo pathway depending on the tumor histotype." (PMID 38755629, 2024). "Around 41% of Triple-Negative Breast Cancers and 19% of basal-like tumours show high BCL2." (PMID 38928195, 2024). "Additionally, Western blot analysis confirmed that siRNA-mediated reduction of Bcl-2 expression significantly enhanced cell apoptosis mediated by PTX or GEM in tumor cells, thereby increasing cell sensitivity to PTX and GEM." (PMID 39452993, 2024). "Western blot analyses further demonstrated upregulation of pro-apoptotic molecules, including Caspase-7, Caspase-3, and Bax, along with downregulation of anti-apoptotic Bcl-2, suggesting enhanced tumor cell apoptosis as a key mechanism driving therapeutic efficacy." (PMID 39777334, 2024). "Also, gene-level RT-PCR and protein-level western-blotting demonstrate superior induction of tumor cell apoptosis via Bax/Bcl-2, caspase 3, 7, and 9, dependent intrinsic mitochondrial apoptosis pathway." (PMID 38609391, 2024). "Among the underlying mechanisms of RL’s action tested parallel in vitro was the proliferation blockage at the G1/S phase of the cell cycle, the increase in the reactive oxygen species levels in the tumor, the upregulation of Bax and Bim proteins, and the upregulation of Bcl-2 and cyclin D1 protein." (PMID 39770078, 2024). "Yet the individual influences of BCL-xL, MCL-1, and BCL-2 on the sensitivity of TNBC cells to chemotherapy, and their regulation by cancer-associated fibroblasts (CAFs), major components of the tumor stroma and key contributors to therapy resistance remain to be delineated." (PMID 38898061, 2024). "When combined with 8 Gy radiation, tumor growth was significantly inhibited, survival was markedly extended, and the anti-apoptotic response was significantly reduced, evidenced by a 6.2-fold increase in the Bax/Bcl-2 ratio compared to radiation alone." (PMID 39766452, 2024). "Crocin increased the Bax/Bcl-2 ratio to induce apoptosis, and tumor proliferation and growth." (PMID 38419885, 2024).
tumor (continued). "Furthermore, BCL2 adenovirus blocked the downregulated YAP-mediated reversion of F. nucleatum-induced chemoresistance in tumor-bearing mouse models treated with 5-Fu." (PMID 38533566, 2024). "Specifically, APS decreased the levels of Bcl-2, β-catenin, c-myc, and Cyclin D1 in cells, suggesting that the mechanism of tumor suppression may be related to the inhibition of Bcl-2 expression by downregulating the Wnt/β-catenin signaling pathway." (PMID 38515577, 2024). "The AbbVie team exploited co-crystal structures of BCL-2 and small-molecule inhibitors to guide their rational design of venetoclax (ABT-199), a first-in-class, highly specific inhibitor of BCL-2, and one of the first approved small-molecule tumor therapeutics that directly blocks a PPI25–28." (PMID 38368459, 2024). "Additionally, bufadienolides can increase the expression of the pro-apoptotic gene Bax and decrease the expression of the anti-apoptotic gene Bcl-2, leading to up-regulation of the apoptotic-related protein caspase and promotion of tumor cell apoptosis 32-34." (PMID 38230219, 2024). "Erianin may exert its anti-tumor effect in DDP-resistance LUAD cells by regulating the Wnt3/β-Catenin/Survivin/Bcl-2/Caspase3/Cyclin D1 axis." (PMID 39605083, 2024). "High expression of pERK1‐2‐positive tumor cells were significantly associated with the nongerminal center cell type and negative BCL2 expression (p = 0.015 and 0.031, each respectively)." (PMID 39404228, 2024). "The consistent changes in the expression of Bax and BCL2 revealed that the Bax/BCL2 signaling pathway might be a common mechanism to inhibit tumor growth, which is a viable direction for creating methods for treating various malignancies." (PMID 38592437, 2024). "Next, the in vitro experiments revealed that the tsRNA-GlyGCC inhibitor suppresses cell proliferation, migration, and formation of tumor spheres by modulating the protein expression of BCL2, BAX and cancer stem cells molecular markers (CD44,CD133, EphB2, LICAM, and LGR5)." (PMID 39153969, 2024). "Additionally, the antiradical mechanisms inside the tumor are disturbed upon the administration of anthraquinones, and the level of Bcl-2 protein is decreased." (PMID 39770078, 2024). "Thus, a novel therapy regimen based on tumour etiology involves blocking the Bcl2 anti-apoptotic protein to overcome the tumour cells' resistance to apoptosis." (PMID 38223131, 2024). "Indeed, many identified miRNAs with both anti-apoptotic and pro-apoptotic properties regulate the expression of apoptotic genes such as phosphatase and tensin homolog (PTEN), caspase-9 and BCL-2, resulting in apoptosis resistance and tumor expansion." (PMID 38891056, 2024). "In various studies, the expression of Bcl-2 was increased with increasing tumor grades." (PMID 39252711, 2024). "SFI hindered tumor progression and might promote apoptosis by increasing the expression of Bax, caspase 3 and decreasing the level of Bcl-2 in NSCLC." (PMID 38809316, 2024). "Activated the ERK and NF-κB pathway in the tumor and enhanced the expression of Bcl-2 in the tumor." (PMID 39906741, 2024). "Moreover, it can increase the ability of BCL-2 inhibitors to kill tumor cells, thereby reducing the chances of tumor escape and ultimately reducing treatment costs." (PMID 39060763, 2024). "In addition, inducing apoptosis in tumor cells appears to be a primary mechanism behind the anti-tumor effects of brown seaweed polysaccharides, involving factors such as Caspases, Bax, Bcl-2, and CDK-2." (PMID 39057425, 2024). "We noted that the gene expression of Bcl2 in T11‐UV was even lower than in T11‐Apobec, which could explain the higher sensitivity of this tumor to PTX relative to T11‐Apobec." (PMID 39553439, 2024). "The increase in BAX/BCL-2 ratio reflected the critical confirmation of tumor cell death." (PMID 38499634, 2024).
tumor (continued). "Taken together, PTPRO can downregulate JAK2/STAT3 phosphorylation, and inhibit oncogenic signals by suppressing expressions of Bcl-2 and Snail; these events may subsequently induce mitochondria-dependent apoptosis and suppress tumor metastasis." (PMID 38182570, 2024). "Thus, in the peritumoral area, tumor transformation of cells most likely occurs, characterized by an increase in Bcl2 expression relative to control groups of animals." (PMID 39063041, 2024). "Importantly, immunofluorescence staining results showed that RSL3 treatment decreased MYB and Bcl-2 expression in the tumor tissues, which was further confirmed in western blot results." (PMID 38956026, 2024). "Additionally, histological analysis of tumor tissues revealed that melittin treatment resulted in a significant reduction in Bcl-2 levels and a concomitant increase in Bax levels (p < 0.05, p < 0.01, p < 0.001)." (PMID 39519238, 2024). "Furthermore, western blot results indicate that VM reduces the expressions of p-PI3K and p-AKT in tumor tissues, along with a decreased ratio of Bcl-2 and Bax protein expressions." (PMID 38372808, 2024). "Conversely, BCL2 has been observed to have tumor-suppressive effects in some studies." (PMID 39507169, 2024). "This could represent a novel concept for pLGG treatment targeting the senescent compartment, with BCL-2 inhibitors both killing senescent tumor cells as well as reprogramming the TME to promote PD-1 inhibitor response." (PMID 38789691, 2024). "Additionally, this group enhanced the fluorescence intensities of CD20 (deep purple) and Caspase-3 (red) in the mouse tumor tissues while suppressing the green fluorescence intensity of Bcl-2." (PMID 39004737, 2024). "Furthermore, our findings are in favor of using TanIIA as an anti-tumor drug on account of its ability to regulate the expression of Bax, Bcl-2 and MMP9." (PMID 39544939, 2024). "Moreover, tumours from mice treated with αCD7/EVs/CytC/siBcl2 also contained more apoptotic cells and reduced Bcl2 protein levels." (PMID 39676736, 2024). "Besides, YY1, SLC1A5, and Bcl-2 protein levels are significantly reduced, while Bax protein level is markedly enhanced in the tumor tissues of Silibinin-treated group." (PMID 38410123, 2024). "Therefore, there are the urgent unmet medical needs in targeting Bcl-2 anti-apoptotic proteins including how to broaden the anti-tumor potential; circumvent the on-target toxicity; and overcome the drug resistance." (PMID 39372954, 2024). "Plant extracts that inhibit bcl-2 gene overexpression hold significant potential as anticancer agents or lead compounds in drug development, given their regulatory influence on cell growth, proliferation, cell cycle, DNA repair, and tumour development." (PMID 39624842, 2024). "The miR-18a levels were further used to correlate with a probability distribution of the tumour aggression score published previously which was derived by fitting a binomial logistic regression model using two genes, ANLN and BCL2, as predictors and tumour grade 3 as the determinant." (PMID 38786043, 2024). "Furthermore, in vivo studies indicate that overexpression of miR-1 targeted Bcl-2 to decrease the tumor volume and weight in nude mice." (PMID 38999923, 2024). "In addition, STC1 also activates ERK and JNK pathway promoting inhibitor of apoptosis proteins (BcL-2 and BcL-xl) and inhibits the expression of pro-apoptotic proteins (Bax, Bak and Bid) for tumor survival." (PMID 38215156, 2024). "Ellagic acid also has been demonstrated to have potent anti-tumor activity by increasing apoptosis through increasing the Bax/Bcl-2 ratio induced caspase-3 in a range of 10–100 μM and has been identified as an anti-aging possibility by results obtained in vivo." (PMID 38256903, 2024).
tumor (continued). "Also, Bcl2 expression displayed diversity in expression profile across the primary tumor cell population." (PMID 38223131, 2024). "WB detection showed that the E7449 group, Xiaoyan decoction and combined treatment group could regulate the apoptosis‐related proteins Bcl‐2 and caspase‐3, indicating that tumour cell apoptosis was promoted by E7449 or Xiaoyan decoction." (PMID 38898581, 2024). "Bcl2 is widely recognized as an important anti-apoptotic molecule in both tumor and normal cells." (PMID 39459003, 2024). "Studies targeting the high expression of BCL2 in tumour cells have revealed that these interactions may further regulate the expression of BCL2 proteins and affect apoptosis." (PMID 38915053, 2024). "Multiple studies have confirmed that the tumor inflammatory tumor microenvironment can activate the axis of COX-2/PGE-2/Bcl-2 pathway, thereby activating the expression of the antiapoptotic gene Bcl-2 in downstream tumor cells and enhancing the antiapoptotic ability of tumor cells." (PMID 38919710, 2024). "However, a recent study by Zhao and colleagues describes that BCL-2 inhibition also enhances the function of classical dendritic cells, unleashing their role in immunosurveillance, promoting T cell immunity and tumour regression." (PMID 38549077, 2024). "The increased expressions of pro-apoptotic caspase-3 and Bax and the downregulation of anti-apoptotic Bcl-2 was observed in CT26 tumor cells treated with enriched occurrence of butyrate producing microbiota which can effectively bind to G protein-coupled receptor 109A (GPR109A)." (PMID 39210613, 2024). "The degradation of BCL-xL and BCL-2 following treatment with 753b was confirmed in tumor tissues." (PMID 38534371, 2024). "Therefore, it is critical to explore new types of small molecule antagonists to target Bcl-2 for tumor therapy." (PMID 37237269, 2023). "Moreover, in our study, we investigated the association between miR-181a-5p and miR-630 target genes (BCL2, LMO3, PTEN, SNAI2, WIF1) expression and clinicopathological characteristics as well as survival rates of NSCLC patients in tumor tissue." (PMID 37697308, 2023). "As seen in other human neoplasms, Bcl-2 has also been assessed as a prognostic marker in uLMS." (PMID 35344084, 2023). "Therefore, suppressing or controlling BCL2 expression can enable tumor cells to resume their natural apoptotic process." (PMID 37396945, 2023). "By suppressing/blocking Bcl-2, the apoptotic process in tumor cells can be restored." (PMID 36613399, 2023). "Also, statistical analyzes in this study showed that there is a significant relationship between high levels of B. fragilis and high levels of BCL2 expression in tumor samples." (PMID 37644520, 2023). "BCL-2 expression is related to good prognosis and may play a vital role in tumor evolution from early to higher stages." (PMID 36751174, 2023). "In addition, it has been shown that miR-21-5p exerts its oncogenic role by targeting multiple tumor suppressor genes, such as Bcl-2, TPM1, PDCD4, and PTEN." (PMID 37444533, 2023). "Knockdown of the PD-L1 gene in preclinical studies was associated with increased levels of BCL-2 and MCL-1 in lymphocytes T, which could increase their survival and promote tumor apoptosis." (PMID 36902139, 2023).
tumor (continued). "One of the underlying mechanisms in tumor resistance is the aberrant activation of PI3K/AKT pathways that upregulates the expression of ABC transporters (P-gp/ABCB1, MRP1/ABCC1, and BRCP/ABCG2), and pro-survival molecules such as Bcl-2 and IAPs." (PMID 37627134, 2023). "When HINT1 is overexpressed in SW480 and McF-7 tumor cells, it leads to a decrease in Bcl-2 levels, an increase in Bax levels, and elevated expression of caspase-9, caspase-8, and caspase-3, ultimately resulting in the induction of apoptosis in tumor cells." (PMID 38068718, 2023). "Thus, not only T cells but also myeloid cells are required for pharmacological BCL2 inhibitors to reduce tumor growth." (PMID 37623817, 2023). "They found that rapamycin, especially when administered with a Beclin-1 plasmid transfection group, demonstrated an increase of the pro-apoptotic factor Bax and low levels of the anti-apoptotic Bcl-2, thus decreasing the viability of tumor cells and promoting apoptosis." (PMID 37720343, 2023). "Mel‐18, a gene promoter regulator, might affect c‐myc, bcl‐2, cyclin D2, and Hox, which induce tumor cell proliferation, metastasis, and angiogenesis." (PMID 36864013, 2023). "Simultaneously, the overexpression of piRNA-MW557525 promoted apoptosis of tumor cells in vivo, as evidenced by the up-regulation of apoptosis-related proteins, cleaved caspase-3 and Bax, and the downregulation of the apoptosis-inhibiting protein, BCL-2." (PMID 37941038, 2023). "The other important targets of miR-181d for tumor suppression are Bcl-2 and KRAS." (PMID 37371047, 2023). "Archival tumor tissues were examined by immunohistochemistry for the expression of bcl-2 and VEGF." (PMID 36766867, 2023). "Indeed, knockout or blockade of IFNAR1 was sufficient to block the enhancement of antigen presentation by BCL2 inhibition in de-iniDCs in vitro, as well as their tumor growth controlling activity in vivo." (PMID 37623817, 2023). "The Bcl-2 inhibitor venetoclax (VEN) is capable of targeting the anti-apoptotic protein Bcl-2, inducing apoptosis in tumor cells without relying on genetic mutations, and has shown great advantages in the treatment of hematologic malignancies." (PMID 38054008, 2023). "For example, TS miR-34a has been identified in PC cells as a regulator of BCL2, resulting in the inhibition of its function and later leading to a reduction in the proliferation of tumor cells, an increase in apoptosis, and heightened sensitivity to chemotherapeutic agents." (PMID 37761870, 2023). "Additionally, proapoptotic genes like BAX lose their ability to act as tumor suppressors due to overexpression of BCL2." (PMID 37396945, 2023). "Furthermore, Th17 cells have the ability to maintain a stem cell-like phenotype by activating the HIF-1α/Notch/Bcl-2 axis, also indicating a correlation between Th17 activity and improved immune responses to tumour antigens." (PMID 36980527, 2023). "A transcriptional deficit of NF‐κB (nuclear factor kappa‐light‐chain‐enhancer of activated B cells) was substantiated by the downregulation of cyclin D1 and of the anti‐apoptotic Bcl2, in line with reduction in tumour cell proliferation and induction of apoptosis, respectively." (PMID 37390227, 2023).